IHH (Indian hedgehog signaling molecule)
Diseases named in the same sentence as IHH in open-access papers (continued):
Sharing a sentence is not in itself a finding about the gene and the disease.
basal cell carcinoma (4 papers, 2010 to 2021). A carcinoma involving the basal cells. "A Smo inhibitor (SMOi) such as GDC-0449 (Vismodegib/Erivedge) developed to treat basal cell carcinoma and medulloblastoma can therefore be used to inhibit IHH signaling." (PMID 26091072, 2015). "HHIP antagonizes all three of the hedgehog family of ligands (SHH, DHH and IHH) and has been shown to be down-regulated in numerous epithelial tumor types with the notable exception of basal cell carcinoma where it is upregulated." (PMID 20860831, 2010). "Pathways that followed were ligand-receptor interactions (IHH, PTCH1) (p-value = 5.76 × 10−5) and signalling in basal cell carcinoma (BMP2, STK36, PTCH1) (p-value = 6.73 × 10−5)." (PMID 28117334, 2017).
colorectal cancer (3 papers, 2013 to 2023). A primary or metastatic malignant neoplasm that affects the colon or rectum. "In colorectal cancer, cancer-initiating cells express the indian hedgehog (IHH) gene, which is present in a bivalent state and contributes to the maintenance of colorectal cancer-initiating cells." (PMID 36810098, 2023). "In patient-derived colorectal cancer-initiating cells, Indian hedgehog (IHH) gene was found to exist in a bivalent state with both the activating H3K4me3 and repressive H3K27me3 histone marks." (PMID 35563709, 2022). "The presence of such a bivalent state in the IHH gene aided stem cell maintenance of the colorectal cancer-initiating cells." (PMID 35563709, 2022). "We found that in case of Colon cancer, along with IHH and SHH ligands, activated RAS/RAK pathway also up-regulated the activity of the GLI proteins in colorectal cancer cell." (PMID 23935937, 2013).
endometrial cancer (3 papers, 2013 to 2020). Primary or metastatic malignant neoplasm involving the endometrium (mucous membrane that lines the endometrial cavity). "Given the role of IHH in negatively regulating the Hedgehog signaling pathway, these data suggest that some high grade endometrial cancers might benefit from targeted Hedgehog pathway intervention." (PMID 23785665, 2013). "In another study, a six-gene prognostic signature, including CTSW, PCSK4, LRRC8D, TNFRSF18, IHH, and CDKN2A, in endometrial cancer was also established using robust likelihood-based survival modeling." (PMID 31781484, 2019).
Infertility (3 papers, 2023 to 2025). "It has been reported that the loss of both DHH and IHH in GC results in the failure of theca cell (TC) development, defective steroidogenesis, and infertility in female mice." (PMID 36766700, 2023). "Interestingly, knockout of both IHH and DHH genes in mice decreased steroidogenesis and caused infertility." (PMID 39468655, 2024). "Mice lacking the expression of both DHH and IHH in GCs (DhhKO; IhhKO) fail to develop the TC cells, and suffer from impaired steroidogenesis and infertility due to failure of ovulation." (PMID 36766700, 2023).
Osteochondroma (3 papers, 2008 to 2015). A common, benign cartiliginous neoplasm arising from the metaphysis of bone. "In conclusion, this first is the first study to demonstrate that loss of Fgfr3 leads to the downregulation of MAPK signaling and enhanced IHH expression, resulting in the formation of chondroma-like lesions, including enchondromas and osteochondromas." (PMID 26091072, 2015). "In the growth plate, IHH regulates chondrocyte proliferation and differentiation in a tightly regulated paracrine feedback loop, together with PTHLH, and deregulated IHH signaling has been implicated in the pathogenesis of osteochondromas." (PMID 21403832, 2011). "In osteochondroma, IHH signalling is still active and is probably cell autonomous." (PMID 18271966, 2008). "PTHLH signalling, which is downstream of IHH and is responsible for chondrocyte proliferation, is absent in osteochondroma, while being upregulated upon malignant transformation of osteochondroma." (PMID 18271966, 2008). "IHH/PTHLH and FGF signaling molecules are mostly absent in osteochondromas and reexpressed with the progression of osteochondroma towards peripheral CHSs." (PMID 21403832, 2011).
adenomyosis (2 papers, 2023 to 2025). The growth of endometrial tissue inside the muscular wall of the uterine corpus. "In the invaginating microenvironment, SFRP5+ epithelial cells stimulated endometrium proliferation and angiogenesis through autocrine and paracrine of IHH, promoting adenomyosis development." (PMID 40190183, 2025). "Abnormally high expression of IHH was spotted in the SFRP5+ epithelial cells of adenomyosis patients." (PMID 40190183, 2025). "Additionally, spatial transcriptomics revealed higher expression of IHH in SFRP5+ epithelial cells which were distributed in endometrial basalis in adenomyosis, which would have been hidden in bulk estimation." (PMID 40190183, 2025). "Further studies are needed to determine the precise involvement of IHH in adenomyosis pathogenesis." (PMID 40190183, 2025). "The IHH expression pattern in epithelial subpopulations shifted during adenomyosis." (PMID 40190183, 2025). "IHH, as well as its transcription factor, receptor, and target gene (SOX17, PTCH1, and HHIP, respectively), exhibiting spatial expression characteristics, were highly expressed in the invaginating site of adenomyosis." (PMID 40190183, 2025).
Anosmia (2 papers, 2019 to 2021). An inability to perceive odors. "Accordingly, we report many patients having anosmia, severe hypotestosteronemia and prepubertal onset hypogonadism associated to rare variants in IHH genes, despite the presence of obesity, thus confirming the poor utility of this parameter to exclude an “organic” disease." (PMID 30669598, 2019). "Thereafter, homozygous mutations of CCDC141, or heterozygous mutations in combination with mutations in other known IHH genes, were reported in Kallmann syndrome and IHH patients, although CCDC141 mutations have never previously been reported in familial self-limited delayed puberty." (PMID 34930920, 2021).
chondrosarcoma (2 papers, 2014 to 2023). A malignant cartilaginous matrix-producing mesenchymal neoplasm arising from the bone and soft tissue. "Then, Using qRT-PCR, we measured the expression of IHH, PTCH1, SMO, and GLI1 and found that their levels were significantly lower in normal articular cartilage compared to any other chondrosarcomas, particularly in dedifferentiated chondrosarcoma." (PMID 37488121, 2023). "Previous studies have documented that during the peripheral chondrosarcoma progression of grade I towards grade III, IHH signaling gradually diminishes and Wnt signaling is lost." (PMID 25144498, 2014).
gastric cancer (2 papers, 2021 to 2022). A primary or metastatic malignant neoplasm involving the stomach. "In this study, we analyzed the expression levels of sonic hedgehog (Shh) signaling pathway genes IHH, BOC, RAB23a and their regulatory miRNAs including MIR-195-5p, MIR-509-3-5p, MIR-6738-3p in gastric cancer patients." (PMID 33811245, 2021). "Analysis of relative expression levels indicated that IHH, BOC, and RAB23 were decreased in 48%, 54%, and 42% of gastric cancer tissues while 32%, 30%, and 34% of cases showed IHH, BOC, and RAB23 overexpression, respectively." (PMID 33811245, 2021). "We also investigated the expression level of Shh signaling genes including IHH, BOC, and RAB23 in gastric cancer patients." (PMID 33811245, 2021). "The expression of IHH, BOC, RAB23, miR-195-5p, and miR-6738-3p decreased significantly with more advanced cancer stage, and miR-509-3-5p expression was significantly decreased during early stages in gastric cancer patients (P < 0.05)." (PMID 33811245, 2021).
melanoma (2 papers, 2020 to 2026). A malignant, usually aggressive tumor composed of atypical, neoplastic melanocytes. "As shown in this study, HA-coated EVs are associated with the release of tumor promoting IHH mitogen from melanoma and these EVs could influence its surrounding microenvironment to melanoma progression." (PMID 31820036, 2020). "The study also identifies a novel feedback regulation between the hedgehog signaling pathway and HA metabolism in melanoma, mediated by EVs carrying HA and IHH." (PMID 31820036, 2020). "The high levels of IHH in HAS3-EVs were surprising, given that most of the reported studies on melanoma and other cancers have largely implicated the role of SHH in the process." (PMID 31820036, 2020). "As shown in our study, one of the mitogens from hedgehog signaling pathway, IHH, is significantly enriched in melanoma derived HAS3-EVs." (PMID 31820036, 2020). "We have also shown that HA synthesis in melanoma cells is associated with the release of HAS3 and IHH in EVs and there is a positive feedback regulation between HA and HH pathways." (PMID 31820036, 2020). "Future studies should focus on the mechanistic details on how HA synthesis mediates the release of IHH in EVs and how the secreted IHH promotes melanoma progression." (PMID 31820036, 2020). "The IHH-c-Myc-claspin axis may help a normal keratinocyte (HaCaT) and a melanoma cell line (WM115) to gain tumorigenic potential, such as increased proliferation; this effect may be due to an enhanced G1/S phase transition and EMT." (PMID 31820036, 2020). "Thus, we suggest that HA synthesis could be one of the stimulating factors for IHH secretion in melanoma cells." (PMID 31820036, 2020). "Thus, IHH could be an important mitogen in melanoma progression that has not been studied and it is interesting that HA signaling contributes to this phenomenon." (PMID 31820036, 2020).
metachondromatosis (2 papers, 2015 to 2023). Metachondromatosis (MC) is a rare disorder characterized by the presence of both multiple enchondromas and osteochondroma-like lesions. "Previous studies have suggested that IHH upregulation contributes to metachondromatosis and that inhibiting IHH signaling suppresses cartilaginous tumorigenesis in Shp2-deficient mice." (PMID 26091072, 2015). "Meanwhile, SHP2 has been shown to have negatively regulated IHH protein and AKT in a mouse metachondromatosis model." (PMID 36768520, 2023). "The IHH inhibitor, PF-04449913, ameliorated metachondromatosis in mice with a lack of SHP2 in CTSK labeled chondroid progenitors." (PMID 36768520, 2023).
osteoporosis (2 papers, 2019 to 2023). A condition of reduced bone mass, with decreased cortical thickness and a decrease in the number and size of the trabeculae of cancellous bone (but normal chemical composition), resulting in increased fracture incidence. "Importantly, both IHH and RUNX2 were differentially expressed between OP patients and controls, suggesting an involvement of these genes in the pathogenesis of osteoporosis." (PMID 38019761, 2023).
prostate carcinoma (2 papers, 2018 to 2022). A carcinoma that arises from epithelial cells of the prostate gland. "Interestingly, lack of IHH association with clinical parameters is also observed in breast and prostate cancers in line with the given cohort." (PMID 29329585, 2018). "In a conditional prostate cancer mouse model in which MYC is expressed under the probasin promoter (PB-MYC), the tumors were highly representative of human prostate cancers, expressed high levels of IHH, and smooth muscle cells were depleted." (PMID 36010600, 2022).
steatosis (2 papers, 2021 to 2022). Increased lipid within the cytoplasm of cells. "TAZ has been reported to promote liver fibrosis by inducing Indian hedgehog (IHH) in hepatocytes 21, which is a secretory factor that activates the Hedgehog signaling pathway in HSCs and mediates steatosis-to-NASH progression." (PMID 33867837, 2021). "Both TAZ and IHH are increased in human livers with NASH but not with simple steatosis, suggesting that hepatocyte TAZ could play a role in promoting NAFLD disease progression, i.e., the transition from steatosis to NASH." (PMID 35805998, 2022).
syndactyly (2 papers, 2019 to 2023). A disease characterized by the presence of syndactyly, including syndromic and non-syndromic forms. "Inversion of the enhancer leads to abnormal activation of WNT6 and causes syndactyly, while duplication of the enhancer and the IHH sequences leads to misexpression of the IHH gene, causing polydactyly." (PMID 37199020, 2023).
acrocallosal syndrome (1 paper, 2025). Acrocallosal syndrome (ACS) is a polymalformative syndrome characterized by agenesis of corpus callosum (CC), distal anomalies of limbs, minor craniofacial anomalies and intellectual deficit. "In Patient 2, OGM identified a mosaic deletion proximal to the IHH gene, causing ectopic regulatory interactions and a phenotype resembling acrocallosal syndrome." (PMID 39941010, 2025).
adenoma (1 paper, 2019). A neoplasm arising from the epithelium. "Consistently, an analysis of patients with APC mutations showed the loss of IHh expression in dysplastic epithelial cells present in adenomas, suggesting that IHh expression is downregulated in response to constitutive β-catenin/TCF signaling." (PMID 31552081, 2019).
amelogenesis imperfecta type 3 (1 paper, 2016). "These include IHH involved in skeletal malformations, ROBO3 involved in horizontal gaze palsy with progressive scoliosis, PCSK9 involved in familial hypercholesterolemia, FAM83H related to amelogenesis imperfecta type 3 and GJA3 associated with congenital cataracts." (PMID 26861414, 2016).
Arthritis (1 paper, 2021). Inflammation of a joint. "2-APB contributes to cartilage protection in vivo by inhibiting the TRPM7 channel and IHH signaling and supports its potential therapeutic value in treatment of arthritis with articular cartilage damage." (PMID 33927631, 2021). "One study demonstrated that TRPM7 silence could reduce the expression of IHH, while the relationship between TRPM7 and IHH and its roles in arthritis cartilage damage remains unclear." (PMID 33927631, 2021).
bone tumors (1 paper, 2019). "Indian Hedgehog (IHH) signaling, a key regulator of skeletal development, is highly activated in cartilage and bone tumors." (PMID 31482846, 2019).
breast tumor (1 paper, 2012). "We have determined that breast tumor cells have an activated Hh pathway characterized by upregulation of the ligand, IHH and transcription factor GLI1." (PMID 22479615, 2012).
cartilage tumors (1 paper, 2014). "Our data, and those of other investigators, suggest that aberrant IHH signaling contributes to cartilage tumor formation." (PMID 24875294, 2014). "Also, an inhibitor of IHH signaling reduced the growth of cartilage tumors in mosaic SHP2 mutant mice." (PMID 24875294, 2014).
colon adenocarcinoma (1 paper, 2024). "As the Hedgehog signaling pathway is also implicated in intestinal development, homeostasis, and colon adenocarcinoma, and IHH is the Hedgehog ligand relevant for the colon adenoma formation, this ligand was included in addition to the most prevalent SHH." (PMID 38731849, 2024).
colon carcinoma (1 paper, 2013). "We found that in our simulation result of Colon cancer model, hedgehog ligands IHH and SHH, RAS in cytoplasm were also activating the GLI transcription factors." (PMID 23935937, 2013). "Experimental evidences have shown that over expression of SHH and IHH can cause up regulation of GLI proteins, or over activation of cytoplasmic protein RAS can also up regulate GLI proteins in Hedgehog pathway and are responsible for Colon cancer." (PMID 23935937, 2013).
dysplasia (1 paper, 2021). A usually neoplastic transformation of the cell, associated with altered architectural tissue patterns. "In contrast, loss of IHH expression can promote the development of dysplasia in colon carcinogenesis via Wnt signaling pathway." (PMID 33811245, 2021).
endothelial dysfunction (1 paper, 2021). In vascular diseases, endothelial dysfunction is a systemic pathological state of the endothelium (the inner lining of blood vessels) and can be broadly defined as an imbalance between vasodilating and vasoconstricting substances produced by (or acting on) the endothelium. "In contrast, in sPE, endometrial ESR1 and IHH are downregulated, decreasing PGR expression and leading to compromised decidualization, endothelial dysfunction, and local immune dysregulation." (PMID 34709177, 2021).
enthesopathy (1 paper, 2023). "The present studies demonstrate that both Hyp and C–/– entheses have increased expression of Gdf5, suggesting that enhanced GDF5 action contributes to the increased BMP and IHH signaling in Hyp and C–/– entheses and, thus, enthesopathy development." (PMID 37490334, 2023). "Taken together, these results support our hypothesis that the impaired 1,25D action due to increased FGF23 levels in Hyp mice contributes to the enhanced BMP and IHH signaling observed in Hyp mice and, thus, to enthesopathy development." (PMID 37490334, 2023). "Based on our findings that 1,25D acts on enthesis cells to suppress BMP and IHH signaling, the decrease in VDR expression in Hyp entheses likely also contributes to the impaired 1,25D action in Hyp entheses, leading to increased BMP and IHH signaling and enthesopathy development." (PMID 37490334, 2023). "1,25D acts directly on enthesis cells to suppress BMP and IHH signaling and can prevent enthesopathy in Hyp and C–/– mice if 1,25D therapy is initiated early in postnatal development, indicating that 1,25D signaling is protective against enthesopathy development." (PMID 37490334, 2023). "Because restoration of 1,25D signaling after enthesopathy has developed does not attenuate BMP and IHH signaling in Hyp and C–/– entheses, the Vdr was deleted in Scx+ cells starting on P30 to determine if loss of 1,25D action in mature entheses leads to enthesopathy." (PMID 37490334, 2023). "Although both WT and Hyp enthesis cells have similar origins, further studies demonstrated that BMP and IHH signaling are increased in Hyp entheses, implicating these signaling pathways in XLH enthesopathy development." (PMID 37490334, 2023). "Our data demonstrate that entheses from mice lacking 1,25D action have increased BMP and IHH signaling early in development, by P14, and that restoration of 1,25D action with systemic 1,25D therapy prevents enthesopathy development." (PMID 37490334, 2023). "Deletion of the Vdr in Scx+ cells throughout enthesis development results in increased BMP and IHH signaling in entheses, whereas deletion of the Vdr in Scx+ cells starting at P30 in Vdrf/f;ScxCreERt+ mice did not lead to enthesopathy." (PMID 37490334, 2023). "Mice lacking Cyp27b1 or Hyp mice were treated with 1,25D starting early in postnatal development or after enthesopathy had already developed, to determine whether enhancing 1,25D action can prevent and/or attenuate BMP and IHH signaling in entheses." (PMID 37490334, 2023). "Hyp entheses have enhanced BMP and IHH signaling and ALP activity by P14, which is prevented if increasing 1,25D action with 1,25D or FGF23Ab therapy is initiated by P2 (prior to development of enthesis changes), suggesting XLH enthesopathy develops in the early postnatal period." (PMID 37490334, 2023). "Also, C–/– mice fed a rescue diet do not have impaired mineralization, yet they develop enthesopathy, as evidenced by the enhanced BMP and IHH signaling and ALP activity in C–/– entheses." (PMID 37490334, 2023). "Deletion of Phex in C–/– and C–/–/F–/– mice (C–/–/Hyp and C–/–/F–/–/Hyp) did not lead to further increased immunoreactivity for BMP and IHH target genes or ALP activity in entheses, suggesting PHEX-specific functions are unlikely to play a dominant role in XLH enthesopathy development." (PMID 37490334, 2023). "C–/– and C–/–/F–/– mice weaned onto a rescue diet have normal mineral ions, yet entheses from these mice develop enthesopathy, indicating that actions specific to 1,25D, independent of its ability to regulate calcium and phosphate homeostasis, suppresses BMP and IHH signaling in entheses." (PMID 37490334, 2023).